KCNK9 (potassium two pore domain channel subfamily K member 9)
Diseases named in the same sentence as KCNK9 in open-access papers (continued):
Sharing a sentence is not in itself a finding about the gene and the disease.
adenomyosis (1 paper, 2022). The growth of endometrial tissue inside the muscular wall of the uterine corpus. "Second, our cross-sectional study was limited in its ability to indicate a causal relationship between KCNK9 expression in the eutopic endometrium and the development of adenomyosis." (PMID 35682653, 2022). "This is the first study to report the association of KCNK9 with adenomyosis." (PMID 35682653, 2022). "We performed a sub-analysis according to endometrial phases, and still found significantly higher expression of the KCNK9 protein on the eutopic endometrium in adenomyosis in both the proliferative and secretory subgroups." (PMID 35682653, 2022). "Hormone-free, antibody-based KCNK9 targeting is a potential therapeutic strategy for adenomyosis-related dysmenorrhea, menorrhagia, and infertility." (PMID 35682653, 2022). "KCNK9, a subgroup of the potassium ion channel protein, was highly expressed in the endometrium of patients with adenomyosis through DNA demethylation." (PMID 35682653, 2022). "Hypomethylated KCNK9 exhibited a higher protein level in the gland cells and vessel epithelia in patients with adenomyosis." (PMID 35682653, 2022). "Our results demonstrated that KCNK9 was highly expressed in both the eutopic and ectopic endometria in adenomyosis." (PMID 35682653, 2022). "KCNK9 was demethylated and highly expressed in the eutopic and ectopic endometria in adenomyosis, which indicates a new field of adenomyosis research." (PMID 35682653, 2022). "This study is the first genome-wide methylation investigation of adenomyosis and revealed a novel ion channel, KCNK9, that may lead to new hormone-independent therapeutic strategies." (PMID 35682653, 2022). "KCNK9 expression was increased in the adenomyosis group compared with the control group." (PMID 35682653, 2022). "First, all the patients with adenomyosis had dysmenorrhea and menorrhagia; the association between KCNK9 and adenomyosis-related symptoms has not yet been established." (PMID 35682653, 2022). "Clinical trials on KCNK9-targeting therapy for symptomatic adenomyosis are warranted." (PMID 35682653, 2022). "Antibody-based KCNK9 targeting may be a promising therapeutic strategy in adenomyosis." (PMID 35682653, 2022). "The KCNK9 expression was not significantly different in the gland cells between the ectopic and eutopic endometria in adenomyosis." (PMID 35682653, 2022). "High expression of KCNK9 in the eutopic and ectopic endometria in patients with adenomyosis but not in normal controls was observed." (PMID 35682653, 2022). "The KCNK9 expression in the endometrial stroma was not significantly different among those with and without adenomyosis (p = 0.174)." (PMID 35682653, 2022).
attention deficit and hyperactivity disorder (1 paper, 2020). "Our data suggest that the influence of KCNK9 on pacemaker frequency and potentially in vivo activity could be feasible as a therapeutical strategy for attention deficit and hyperactivity disorder (ADHD)." (PMID 31980599, 2020).
autism (1 paper, 2019). Persistent deficits in social interaction and communication and interaction as well as a markedly restricted repertoire of activity and interest as well as repetitive patterns of behavior. "KCNK9 has been reported within a list of gene expression biomarkers for autism in patent US20130210650A1." (PMID 31717838, 2019).
colitis (1 paper, 2024). Inflammation of the colon. "Mice lacking the gene KCNK9 were found to be particularly susceptible to DSS-induced colitis." (PMID 38933260, 2024).
colon adenocarcinoma (1 paper, 2023). "The authors further examined the relationship between KCNK9 expression level and clinicopathologic characteristics of colon adenocarcinoma patients." (PMID 36905879, 2023). "In order to determine KCNK9 expression in colon adenocarcinoma cells, the authors first analyzed the expression data of KCNK9 using the TCGA database." (PMID 36905879, 2023). "The results showed that KCNK9 expression was upregulated in colon adenocarcinoma cells." (PMID 36905879, 2023).
colon carcinoma (1 paper, 2023). "KCNK9 was overexpressed in colon cancer cells and was associated with a shorter Overall Survival (OS), a shorter Disease-Specific Survival (DFS), and a shorter Progression-Free Interval (PFI) of colon cancer patients." (PMID 36905879, 2023). "This research aimed to investigate the suppressive effects of genistein on colon cancer cells and the association between the application of genistein and KCNK9 expression level." (PMID 36905879, 2023). "Moreover, the KCNK9 expression level was higher in the subgroup of a tumor with higher malignancy, which indicated that KCNK9 expression was associated with the malignant degree of colon cancer." (PMID 36905879, 2023). "Cell invasion assay revealed that the knockdown of KCNK9 decreased the invasion ability of colon cancer cells." (PMID 36905879, 2023). "In order to further explore the relationship between KCNK9 expression and the prognosis of patients with colon cancer, the survival curve of patients with tumor M1 stage in the TCGA COAD cohort was analyzed using Kaplan-Meier method." (PMID 36905879, 2023). "In vitro experiments in both cell lines proclaimed that the knockdown of KCNK9 inhibited the malignant phenotype of colon cancer cell lines." (PMID 36905879, 2023). "In order to further explore the role of KCNK9 expression in colon cancer, cells were transfected with short hairpin RNA (shRNA) to interfere with the KCNK9 expression level." (PMID 36905879, 2023). "The Cancer Genome Atlas (TCGA) database was used to study the correlation between the KCNK9 expression level and the prognosis of colon cancer patients." (PMID 36905879, 2023). "Compared with normal colon epithelial cells, KCNK9 expression was also upregulated in colon cancer cell lines." (PMID 36905879, 2023). "A mouse model of liver metastasis of colon cancer cells was established using the KCNK9 knockdown cell line and control cell line of SW480." (PMID 36905879, 2023). "The results of the present study demonstrated a new antitumor mechanism of genistein that application of genistein downregulated KCNK9 expression and suppressed the malignant phenotype of colon carcinoma by suppressing the Wnt/β-catenin signaling pathway in vitro." (PMID 36905879, 2023). "In the present study, the authors provided new evidence that genistein could inhibit cell replication and induce apoptosis of colon cancer cells by attenuating the Wnt/β-catenin signaling pathway, which could be mediated by KCNK9." (PMID 36905879, 2023). "In vivo experiments revealed that silencing of KCNK9 or application of genistein could inhibit hepatic metastasis from colon cancer." (PMID 36905879, 2023). "At the same time, the high KCNK9 expression level was associated with the poorer prognosis of colon cancer patients, suggesting that KCNK9 may act as a protooncogene in colon cancer." (PMID 36905879, 2023). "An elevated KCNK9 expression level in patients with colon cancer was detected." (PMID 36905879, 2023). "Genistein inhibited the occurrence and progression of colon cancer through Wnt/β-catenin signaling pathway that could be mediated by KCNK9." (PMID 36905879, 2023). "Despite these limitations, this study demonstrated that genistein could lower KCNK9 expression and the subsequent activation of the Wnt/β-catenin signaling pathway to suppress colon cancer." (PMID 36905879, 2023). "HT29 and SW480 colon cancer cell lines were cultured to examine the inhibitory effects of KCNK9 and genistein on colon cancer in vitro, and a mouse model of colon cancer with liver metastasis was established to verify the inhibitory effect of genistein in vivo." (PMID 36905879, 2023). "•KCNK9 mediates the inhibitory effects of genistein on colon cancer liver metastasis." (PMID 36905879, 2023). "Western blotting was applied to detect KCNK9 expression in colon cancer tissues and cells." (PMID 36905879, 2023).
colon carcinoma (continued). "The results of RT-qPCR and Western blotting showed that genistein could significantly reduce the KCNK9 expression level in colon cancer cells." (PMID 36905879, 2023). "•High KCNK9 expression level is correlated with colon cancer patients' poor survival." (PMID 36905879, 2023). "Wound healing assay showed that the inhibition of KCNK9 could restrain the migration capacity of colon cancer cells." (PMID 36905879, 2023). "Receiver Operating Characteristic (ROC) curve analysis showed that KCNK9 expression level could be used as a predictive marker for colon cancer." (PMID 36905879, 2023). "Moreover, the knockdown of KCNK9 could further enhance the inhibitory effect of genistein on the viability of colon cancer cells." (PMID 36905879, 2023). "In vitro experiments showed that downregulation of KCNK9 or genistein application could suppress cell proliferation, migration, and invasion abilities, induce cell cycle quiescence, promote cell apoptosis, and reduce epithelial-mesenchymal transition of the colon cancer cell line." (PMID 36905879, 2023). "For the purpose of finding the KCNK9-related pathway, the GSEA was employed using transcriptome data of colon cancer samples from the Gene Expression Omnibus (GEO) database." (PMID 36905879, 2023). "Next, KCNK9 expression was identified in normal colon epithelial cell line (FHC) and two colon cancer cell lines, HT-29 and SW480, by RT-qPCR and Western blotting." (PMID 36905879, 2023).
dyslipidemia (1 paper, 2018). "Another KCNK9 around the suggestive SNP rs13251143 also has evidence for dyslipidemia." (PMID 30498476, 2018).
Globozoospermia (1 paper, 2015). Any structural anomaly of the acrosome resulting in a round sperm head. "Six imprinted genes showed different 5hmC patterns between normal and abnormal sperm (GDAP1L1, GNAS, KCNK9, LIN28B, RB1, RTL1), and five imprinted genes showed different 5hmC patterns between normal and globozoospermia sperm (KCNK9, LIN28B, RB1, SLC22A18, ZDBF2)." (PMID 25762640, 2015).
ischemic stroke (1 paper, 2010). A stroke disorder caused by obstruction of blood flow to the brain, due to thrombotic (local blood clot formation) or embolic (due to a blood clot or other material traveling from another site) event. "The TASK subfamily of channels, notably TASK-1 (KCNK3) and TASK-3 (KCNK9), have now been shown to modulate inflammation and neurodegeneration in EAE and probably also ischemic stroke, thus identifying new potential molecular targets for the therapy of inflammatory and degenerative CNS disorders." (PMID 20356357, 2010).
liver cancer (1 paper, 2019). An epithelial or non-epithelial malignant neoplasm that arises from the liver. "We observed reduced expression of KCNK2, KCNK15, and KCNK17 in liver cancer, as well as overexpression of KCNK9, all of which correlated with a better prognosis for HCC patients per survival analyses." (PMID 31581133, 2019).
Sleep apnea (1 paper, 2022). An intermittent cessation of airflow at the mouth and nose during sleep is known as sleep apnea. "However, a clear mechanistic link between TASK-1 and sleep apnea remains unproven and is further complicated by the propensity of TASK-1 subunits to co-assemble with related TASK-3 (KCNK9) subunits to form new heteromeric TASK-1–TASK-3 channels in cells where both genes are coexpressed." (PMID 36195757, 2022).
squamous cell lung carcinoma (1 paper, 2016). A carcinoma arising from squamous bronchial epithelial cells. "In squamous cell lung cancer, the 2-year relative survival rates of low KCNK9 expressers increased by 58% compared with high expressers." (PMID 26842342, 2016).
thyroid cancer (1 paper, 2020). "However, KCNK1, KCNK6, KCNK7, KCNK9, KCNK10, KCNK13 and KCNK16 mRNA expressions were not related to the prognosis of patients with thyroid cancer." (PMID 32742463, 2020).
cancer (34 papers, 2013 to 2026). A tumor composed of atypical neoplastic, often pleomorphic cells that invade other tissues. "The KCNK9 gene, commonly referred to as TASK-3, was associated with cancer due to its overexpression in human tumors and its ability to promote tumor survival and growth." (PMID 35656548, 2022). "In both cancer cells and mammary epithelial cells from high-risk women, we observed hypomethylation of the KCNK9 DMR." (PMID 34885139, 2021). "KCNK9, a member of K2P family, is implicated in cancer, owing to its overexpression in human tumours and its ability to promote neoplastic cell survival and growth." (PMID 26842342, 2016). "The TASK3 gene (Kcnk9) is overexpressed in several types of human carcinomas which has been associated with resistance towards apoptosis." (PMID 24493757, 2014). "However, the underlying mechanism that how KCNK9 exerts its cancer-promoting function remains to be further studied and verified." (PMID 36905879, 2023). "KCNK9 has also been implicated in cancer based on genetic evidence." (PMID 26842342, 2016). "Such increased understanding of the epigenetic regulation of KCNK9 will be of great value in determining the role that expression of this gene has in the development and progression of cancers and in developing new treatment methods." (PMID 34885139, 2021). "The data show that mRNA expression of KCNK1, KCNK7, and KCNK9 is upregulated in cancer tissues while KCNK2, KCNK3, KCNK5, KCNK10, KCNK13, KCNK15, and KCNK17 levels are decreased compared to controls." (PMID 31581133, 2019). "KCNK9 is upregulated in breast and colorectal cancer, and increases tumor tolerance to hypoxia and a serum-free environment by inhibiting apoptosis." (PMID 31581133, 2019). "Depending on the cancer type and method used to manipulate channel function, KCNK9 had different roles in tumorigenicity." (PMID 26842342, 2016). "Given that Y4 binds and internalizes hKCNK9 in a K2P subtype-specific manner, it affords an advantageous strategy to investigate the role of endogenous KCNK9 in cancer biology." (PMID 26842342, 2016). "In our study, by comparing Y4 and H8, we found that the degree of KCNK9 conductance inhibition correlates with antibody's anti-cancer effect in vivo." (PMID 26842342, 2016). "We characterized antibody-based KCNK9 targeting and found it effectively inhibited cancer cell survival, tumour growth and metastasis." (PMID 26842342, 2016). "In this study, the authors developed a specific monoclonal antibody against the extracellular domain of KCNK9 and show that it inhibits cancer growth and metastasis in vivo through both cell autonomous and immune-dependent cellular cytotoxicity." (PMID 26842342, 2016). "The addition of Y4 to KCNK9-expressing carcinoma cells reduces cell viability and increases cell death." (PMID 26842342, 2016). "The present study highlighted the cancer-promoting effect of KCNK9 through in vitro experiments." (PMID 36905879, 2023). "In addition, TASK-3 (Kcnk9) has been shown to have oncogenic potential in several types of human carcinomas." (PMID 24009588, 2013). "Across 33 TCGA tumor types, the pan-cancer co-expression analysis identified three transcripts—IL1RAPL1, KCNK9, and TMEM169—that consistently tracked with OPCML." (PMID 41561740, 2025). "KCNK9 is a member of the KCNK family and is overexpressed in malignancies, indicating its cancer-promoting function." (PMID 36905879, 2023). "TASK-3(KCNK9) promotes the proliferation and survival of cancer cells by enhancing their resistance to hypoxia and serum deprivation." (PMID 36703789, 2022). "KCNK9 and its gene product, TASK3, is of interest for human health studies, as overexpression is strongly tied to cancer." (PMID 34885139, 2021). "Both KCNK9 and ADCY7 are often found overexpressed in human cancers." (PMID 37958378, 2023). "Inhibition of KCNK9 via a dominant-negative mutant or short hairpin RNA was shown to inhibit cancer cell proliferation by 25∼65% (refs 6, 22)." (PMID 26842342, 2016).
tumor (19 papers, 2010 to 2025). "Studies on cBioportal were analyzed for mutation frequencies of GPR31, GPR151, KCNK3, and KCNK9 in the investigated tumor entities." (PMID 35011589, 2021). "In addition, in vitro experiments indicate that the overexpression of KCNK9 promotes tumor formation and is associated with tumor resistance to hypoxia and serum deprivation." (PMID 28974231, 2017). "The results revealed that KCNK9 expression level was correlated with tumor N stage, M stage, and pathological stage, and was also associated with residual tumors and a history of colon polyps." (PMID 36905879, 2023). "In keeping with this, an artificial point mutation (G95E) in KCNK9 abolished TASK-3 channel activity and oncogenic activities, including proliferation, resistance to apoptosis, and tumor cell growth." (PMID 33562306, 2021). "This would support the findings that KCNK9 targeting by Y4 reduced proliferative index and decreased tumour burden in vivo." (PMID 26842342, 2016). "KCNK9 expression was upregulated in tumor tissues at the protein level." (PMID 36905879, 2023). "Moreover, the addition of Y4, a monoclonal antibody against the TASK-3 channel extracellular domain, to KCNK9-expressing carcinoma cells can inhibit tumor growth and metastasis." (PMID 36500386, 2022). "However, how endogenous KCNK9 contributes to neoplasia and its potential as a therapeutic target remain elusive due to the lack of specific modulators of KCNK9 functions." (PMID 26842342, 2016). "This supports the notion that KCNK9 promotes tumour growth and may be a therapeutic target in KCNK9-expressing malignancies." (PMID 26842342, 2016). "Hence it is plausible that KCNK5/KCNK9 overexpression related to TN-subtype may be functionally related to specific tumor CpG loci hypomethylation." (PMID 28899398, 2017). "To confirm our conclusions above, we used qRT-PCR to measure the mRNA levels of KCNK2, KCNK9, KCNK15, and KCNK17 in 90 pairs of HCC specimens and matched non-tumor specimens, which were surgically removed from HCC patients." (PMID 31581133, 2019). "Next, we used Western Blot to measure the protein levels of KCNK2, KCNK9, KCNK15, and KCNK17 in four pairs of HCC tissues and matched non-tumor tissues." (PMID 31581133, 2019). "The data showed that mRNA levels of KCNK7, KCNK9 and KCNK10 correlated inversely with tumor differentiation degree." (PMID 31581133, 2019). "Furthermore, Y4 could have anti-tumour effects independent of KCNK9 function." (PMID 26842342, 2016).
neurodevelopmental disorder (4 papers, 2020 to 2024). A behavioral and cognitive disorder with onset during the developmental period that involves impaired or aberrant development of intellectual, motor, or social functions. "KCNK9 is less constrained than other genes causing dominant neurodevelopmental disorders, however, and 9/19 variants fall in constrained coding regions (CCR) > 95th percentile." (PMID 35698242, 2022). "In summary, KIS is a neurodevelopmental disorder caused by a spectrum of pathogenic variants on the maternal allele of the paternally imprinted KCNK9 gene." (PMID 35698242, 2022). "Also, we have identified 15 de novo variants in genes that were previously implicated in ASD or related neurodevelopmental disorders (PHF21A, WASF1, TCF20, DEAF1, MED13, CREBBP, KDM6B,SMURF1, ADNP, CACNA1G, MYT1L, KIF13B, GRIA2, CHM, and KCNK9)." (PMID 38572415, 2024).
KCNK9 also shares sentences with these, for which no sentence is quoted: ovarian carcinoma (5 papers); gastric adenocarcinoma (4); Cerebral ischemia (3); Intellectual disability (3); adenoma (2); adrenal cortical adenocarcinoma (2); cardiac hypertrophy (2); colorectal cancer (2); deafness (2); hyperaldosteronism (2); Hypertension (2); lung adenocarcinoma (2); pulmonary arterial hypertension (2); rectal cancer (2); Stroke (2); adenocarcinoma (1); alcohol dependence (1); Arrhythmogenic right ventricular dysplasia (1); atrial fibrillation (1); autism spectrum disorder (1); basal cell carcinoma (1); Chediak-Higashi syndrome (1); cleft palate (1); Cohen syndrome (1); colon polyps (1); cyst (1); developmental delay (1); diabetes (1); Dysmenorrhea (1); Escobar syndrome (1).